RNU6-1161P (RNA, U6 small nuclear 1161, pseudogene)
Gene: Small nuclear RNA gene on chromosome 22 (45,624,531 to 45,624,632, reverse strand). Ensembl gene ENSG00000251985.
Homologues: Orthologues: chimpanzee U6 (100% identical), pig U6 (64% identical), mouse Gm24223 (41% identical). Paralogues in human: RNU6-434P (83% identical), RNU6-1075P (80% identical), RNU6-29P (80% identical), RNU6-1145P (79% identical), RNU6-1190P (79% identical), RNU6-181P (79% identical), RNU6-310P (79% identical), RNU6-393P (79% identical), RNU6-41P (79% identical), RNU6-637P (79% identical), RNU6-753P (79% identical), RNU6-1152P (78% identical), and 1286 more.